GPAT2 (glycerol-3-phosphate acyltransferase 2, mitochondrial)
Description:
Transfers an acyl-group from acyl-ACP to the sn-1 position of glycerol-3-phosphate producing a lysophosphatidic acid (LPA), an essential step for the triacylglycerol (TAG) and glycerophospholipids. In vitro also transfers an acyl-group from acyl-ACP to the LPA producing a phosphatidic acid (PA). Prefers arachidonoyl-CoA as the acyl donor. Required for primary processing step during piRNA biosynthesis. Molecular mechanisms by which it promotes piRNA biosynthesis are unclear and do not involve its acyltransferase activity.
Synonyms: CT123
Tractability: Antibody: UniProt predicts a signal peptide or a membrane-spanning region. PROTAC: ubiquitination databases record sites on it.
Gene: Protein-coding gene on chromosome 2 (96,021,946 to 96,039,451, reverse strand). Ensembl gene ENSG00000186281.
Subcellular location: Mitochondrion outer membrane
Subcellular location (Human Protein Atlas): Mitochondria
Pathways (Reactome):
Metabolism: Synthesis of PA; Triglyceride biosynthesis
Gene Ontology:
Molecular function: glycerol-3-phosphate O-acyltransferase activity; 1-acylglycerol-3-phosphate O-acyltransferase activity; acyltransferase activity
Biological process: glycerol-3-phosphate metabolic process; glycerophospholipid metabolic process; phosphatidic acid biosynthetic process; piRNA processing; triglyceride biosynthetic process; CDP-diacylglycerol biosynthetic process; lipid metabolic process
Cellular component: mitochondrion; mitochondrial outer membrane
Genetic constraint (gnomAD): Loss-of-function variants: 51 observed, 60.26 expected, observed/expected ratio (o/e) 0.85, 90% interval 0.68 to 1.07. The upper end of that interval is the gene's LOEUF score, 1.07, which puts it in group 4 of 6, group 1 being the genes least tolerant of losing a copy. Missense variants: 509 observed, 600.04 expected, observed/expected ratio (o/e) 0.85, 90% interval 0.79 to 0.91. Synonymous variants: 220 observed, 258.13 expected, observed/expected ratio (o/e) 0.85, 90% interval 0.76 to 0.95.
Homologues: Orthologues: chimpanzee GPAT2 (98% identical), macaque GPAT2 (90% identical), rat Gpat2 (84% identical), mouse Gpat2 (83% identical), rabbit GPAT2 (81% identical), guinea pig GPAT2 (81% identical), dog GPAT2 (77% identical), tropical clawed frog GPAT2 (40% identical), zebrafish gpat2 (30% identical), Drosophila melanogaster mino (19% identical), Caenorhabditis elegans acl-6 (19% identical). Paralogues in human: GPAM (32% identical), GNPAT (15% identical).
Diseases named in the same sentence as GPAT2 in open-access papers:
GPAT2 is named in the same sentence as 16 diseases in open-access papers, as found by Europe PMC text mining. Sharing a sentence is not in itself a finding about the gene and the disease. The quoted sentences say what the papers report.
breast carcinoma (7 papers, 2014 to 2025). "GPAT2, particularly, is significantly upregulated in breast cancer cells, which is associated with poor clinical outcomes." (PMID 40002245, 2025). "Specifically, downregulation of GPAT2 has been associated with malignancy, proliferation, and survival in breast cancer cell lines." (PMID 39351361, 2024). "Very recently, the same group further found that nine micro-RNAs (miRNAs), which are usually upregulated in breast cancer and are associated with a worse survival prognosis, are downregulated in the GPAT2-silenced MDA-MB-231 cells." (PMID 30813330, 2019). "Consistent with these in vitro results, the inoculation of GPAT2-deficient breast cancer cells fail to grow in the nude mice." (PMID 30813330, 2019). "We also identified 9 miRNAs downregulated by GPAT2 silencing that are usually upregulated in breast cancer and are associated with a worse survival prognosis." (PMID 29963267, 2018). "Additionally, when histopathological variables were analyzed, GPAT2 showed a positive association with the histological grade, which is also characteristic of CT genes, since they are preferentially expressed in high grade breast cancers." (PMID 24967918, 2014). "GPAT2 silencing alters the small non-coding RNA landscape, resulting in a more differentiated phenotype of breast cancer cells." (PMID 40002245, 2025). "The knockout of GPAT2 in the breast cancer cell line (MDA-MB-231 cells) markedly diminishes proliferation and migration." (PMID 30813330, 2019). "GPAT2 knockdown in MDA-MB-231 breast cancer cells diminished cell proliferation, anchorage independent growth, migration and tumorigenicity, and increased staurosporine-induced apoptosis." (PMID 29963267, 2018). "In the present work, we report for the first time the morphological differences between cells that express or subexpress a cancer-testis gene GPAT2 in a breast cancer cellular model." (PMID 29211789, 2017). "In this work, we used AFM to evaluate the phenotypic consequence of GPAT2 expression in cancer cells, and to correlate human GPAT2 expression with the cellular processes that exacerbate the tumoral phenotype in a breast cancer cell model." (PMID 29211789, 2017). "In this study, we explored GPAT2 protein expression in breast carcinoma tissues, and found that 36% of breast tumors express this protein." (PMID 24967918, 2014). "GPAT2 showed the highest expression level in the breast cancer cell line MDA-MB-231, which is characterized as a very aggressive tumor, because it is highly proliferative and tumorigenic." (PMID 24967918, 2014). "Using a bioinformatics approach, we found that GPAT2 is highly expressed in melanoma, lung, prostate and breast cancer, and we validated GPAT2 expression at the protein level in breast cancer by immunohistochemistry." (PMID 24967918, 2014). "We chose the MDA-MB-231 cell line derived from human breast carcinoma because these cells express high levels of GPAT2." (PMID 24967918, 2014). "Its mitochondrial isoform, GPAT2, is highly expressed in PCa and promotes growth and tumorigenicity of breast cancer cells in vitro, but it is unclear whether GPAT2 responds to C. acnes like its isoform." (PMID 41514871, 2025). "In addition, miRNAs known to be overexpressed in breast cancer tumors with poor prognosis where found downregulated in GPAT2-silenced cells." (PMID 29963267, 2018). "We found a significant overlap between the miRNAs differentially expressed in the comparison normal breast vs breast cancer obtained from YM500 database, with those found affected by GPAT2 silencing in the present study." (PMID 29963267, 2018). "Consequently, the overexpression of enzymes involved in triglyceride synthesis, e.g., GPAT2, LPIN1, and DGAT, is a common alteration in breast cancer." (PMID 40002245, 2025).
breast carcinoma (continued). "Considering that GPAT2 has been involved in piRNA biogenesis in germline stem cells and that GPAT2 is highly expressed in MDA-MB-231 cells, we asked whether GPAT2 could be also involved in piRNA metabolism in breast cancer cells." (PMID 29963267, 2018).
melanoma (2 papers, 2014 to 2018). A malignant, usually aggressive tumor composed of atypical, neoplastic melanocytes. "Statistical analysis revealed that tumor locations with higher percentage of samples in the “high GPAT2 expression group” (p<0.01) were: melanoma (44%), lung (41%), prostate (65%), and breast tumor (42%)." (PMID 24967918, 2014). "GPAT2, also known as “cancer-testicular antigen”, is highly expressed in several cancer types (such as lung, melanoma, breast, and prostate cancer) and cancer-derived human cell lines, in which GPAT2 expression is associated with histological grading of the tumor." (PMID 29799006, 2018).
breast adenocarcinoma (1 paper, 2014). "To analyze GPAT2 expression at the protein level in human breast adenocarcinomas, we performed immunohistochemistry (using an anti-GPAT2 antibody previously validated in our lab) on a commercial breast tissue microarray." (PMID 24967918, 2014).
myeloma (1 paper, 2014). "Human GPAT2 has been proposed as a novel CT gene candidate based only on the fact that GPAT2 mRNA expression profile was selective to the testis and to myeloma cells." (PMID 24967918, 2014). "Based on a study of multiple myeloma, GPAT2 was proposed to be a novel “cancer-testis” gene (CT gene) candidate." (PMID 24967918, 2014).
schizophrenia (1 paper, 2025). A major psychotic disorder characterized by abnormalities in the perception or expression of reality. "Furthermore, we identified six genes—GRK2, KLF3, TAOK2, ARFGAP45, AP1M1, and GPAT2—that were shared across gene sets associated with both brain function and clinical symptoms, suggesting a common transcriptional basis for these features of schizophrenia." (PMID 41271614, 2025). "The downregulation of GPAT2 in schizophrenia suggests neuronal/glial damage and lipid metabolism dysregulation, aligning with schizophrenia pathophysiology." (PMID 41271614, 2025). "An intersection analysis revealed six genes-GRK2, KLF3, TAOK2, ARFGAP45, AP1M1, and GPAT2-common to both brain function and clinical symptomatology gene sets, highlighting a shared genetic etiology in schizophrenia’s neuroimaging and clinical manifestations." (PMID 41271614, 2025). "While no prior studies have linked GPAT2 to schizophrenia, its role in generating phosphatidic acid—a precursor to membrane phospholipids essential for cell membrane structure, function, and inter-neuronal interactions—is intriguing." (PMID 41271614, 2025). "Consequently, GPAT2 may serve as a potential biomarker for aiding in the diagnosis of schizophrenia." (PMID 41271614, 2025).
triple-negative breast carcinoma (1 paper, 2018). An invasive breast carcinoma which is negative for expression of estrogen receptor (ER), progesterone receptor (PR), and human epidermal growth factor receptor 2 (HER2). "In this study, we described how the landscape of sncRNAs is affected by GPAT2 silencing in triple-negative breast cancer MDA-MB-231 cells, which normally express GPAT2." (PMID 29963267, 2018).
cancer (9 papers, 2014 to 2024). A tumor composed of atypical neoplastic, often pleomorphic cells that invade other tissues. "Additionally, cancer-specific loss of isozyme diversity, exemplified by lower GPAT2 RNA levels in TNBC than in GPAT148, suggests potential mitigation of LPA production upon SNRNP200 inhibition." (PMID 39285160, 2024). "In MDA-MB-231 breast cancer cells, “cancer-testis gene” Glycerol-3-phosphate acyltransferase-2 (GPAT2) showed regulation on the expression of piRNAs and tRNA-derived fragments." (PMID 34295823, 2021). "The most GPAT2-regulated piRNAs are single copy in the genome and previously found to be upregulated in cancer cells." (PMID 34295823, 2021). "We also determined that GPAT2 behaves as a cancer testis gene: its expression is restricted to testis under physiological conditions, but it is ectopically overexpressed in cancer cells, contributing to tumor phenotype." (PMID 29963267, 2018). "In pathological conditions, we have reported that human GPAT2 is overexpressed in several types of cancers and cancer-derived human cell lines, and that its expression contributes to the tumor phenotype." (PMID 29211789, 2017). "GPAT2 is a mitochondrial isoform primarily expressed in testis under physiological conditions, and overexpressed in several types of cancers and cancer-derived human cell lines where its expression contributes to the tumor phenotype." (PMID 29211789, 2017). "Because GPAT2 has been proposed to be a novel CT gene and in order to validate its high expression in human testis and in cancers, we performed an in silico analysis of GPAT2 mRNA expression." (PMID 24967918, 2014). "GPAT2 gene knockdown in this cancer cell model showed that GPAT2 can promote cell tumorigenicity, proliferation and survival." (PMID 24967918, 2014). "To determine out which tumor locations express high GPAT2 mRNA levels, we analyzed a compiled dataset of 1693 samples derived from 13 different cancer types." (PMID 24967918, 2014). "We explored GPAT2 distribution in different cancer tissues, we detected GPAT2 expression at protein level in cancer cells and we obtained evidence that GPAT2 expression is epigenetically regulated." (PMID 24967918, 2014). "In conclusion, we confirm GPAT2 as a cancer testis gene and that its expression contributes to the tumor phenotype of MDA-MB-231 cells." (PMID 24967918, 2014). "We also evaluated GPAT2 expression profile in cancer cell lines in order to get an in vitro model of GPAT2 expressing cell line." (PMID 24967918, 2014). "Our present data linking GPAT2 to tumorigenesis open the possibility of considering GPAT2 as a potential target for treatment of highly aggressive cancers." (PMID 24967918, 2014). "GPAT2 is also highly expressed in tumors and was suggested to belong to a class of “cancer-testis” genes, whose expression is normally low in somatic tissues but may be upregulated in cancers of various origins." (PMID 34890643, 2022). "The GPAT2 expression pattern in different tumors is consistent with other CT genes in human cancer." (PMID 30813330, 2019). "The aim of this study was to determine whether GPAT2 behaves as a CT gene and to evaluate the phenotypic consequence of GPAT2 expression in cancer cells." (PMID 24967918, 2014). "Fourteen of the mutated genes in this tumor are involved in metabolism (endogenous molecules as well as drugs), small molecule biochemistry, and cancer: AATF, ATF71P, CRIPAK, CROCC, CYP2A6, DOCK5, GPAT2, KRTAP4–9, LSM14A, MUC2, MYO1F, RHOQ, SUFU, and UTRN." (PMID 29259192, 2017). "In conclusion, GPAT2 silencing quantitatively and qualitatively affects the population of PIWI-interacting RNAs, tRNA derived fragments and miRNAs which, in combination, result in a more differentiated cancer cell phenotype." (PMID 29963267, 2018).
tumor (6 papers, 2014 to 2023). "In this regard, tumor cells with diminished GPAT2 expression had lower rates of cellular proliferation and migration and lower tumorigenicity in mouse xenograft models." (PMID 29211789, 2017). "The dramatic reduction of the MDA-MB-231 tumor phenotype by GPAT2 silencing was also evident in vivo, because knocked down cells were unable to generate tumor xenografts in nude mice." (PMID 24967918, 2014). "Using data available in public databases, we analyzed the GPAT2 expression profile in human tumor samples and found that in each tumor location only a fraction showed high GPAT2 expression levels." (PMID 24967918, 2014). "In order to evaluate the contribution of GPAT2 to the tumor phenotype, we silenced its expression in MDA-MB-231 cells." (PMID 24967918, 2014). "Only 11% of Grade I/II tumor samples were positive for GPAT2 protein expression, compared to 55% for Grade III samples (p<0.05)." (PMID 24967918, 2014). "GPAT2 plays a critical role in spermatogenesis and tumor development." (PMID 29799006, 2018). "Considering that GPAT2 knockdown reduced tumor phenotype, we hypothesized that this action could be related to changes in specific piRNAs associated with cell proliferation." (PMID 29963267, 2018). "These GPAT2-induced changes are consistent with its proposed function as a tumor-promoting gene, and might be used as a phenotypic differentiation marker." (PMID 29211789, 2017). "In TCGA-LIHC paired samples, the transcript levels of GPAT2 and GPAT4 were found to be significantly higher in tumor tissue samples than in the respective adjacent normal tissue samples." (PMID 36845084, 2023).
hematological cancers (1 paper, 2014). "On the other hand, renal (55%), colorectal (47%), hepatocellular (64%), basal cell (67%) and hematological cancers (AML, 47%; UCSD CLL, 51%) showed a significantly higher percentage of samples with low expression of GPAT2 (p<0.01)." (PMID 24967918, 2014).
infection (1 paper, 2025). The state of being infected such as from the introduction of a foreign agent such as serum, vaccine, antigenic substance or organism. "In this study, we found that the expression levels of the EC marker genes CUT1, GPAT2, and LACS4 were significantly reduced in most epidermal cells during the infection process, particularly at the T2 stage." (PMID 40756631, 2025).
GPAT2 also shares sentences with these, for which no sentence is quoted: breast tumor (1 paper); Hepatic steatosis (1); infertile (1); Insulin resistance (1); pancreatic cancer (1); prostate carcinoma (1).